BRCA1 (BRCA1 DNA repair associated)
Diseases named in the same sentence as BRCA1 in open-access papers (continued):
Sharing a sentence is not in itself a finding about the gene and the disease.
breast cancer (continued). "For example, BRCA1, a classic TSG which plays an essential role in the occurrence and development of breast cancer, has been found to frequently exhibit promoter hypermethylation in breast cancer tissues." (PMID 30918105, 2019). "In healthy BRCA1/2 mutation carriers, bilateral risk-reducing mastectomy (BRRM) strongly reduces the risk of developing breast cancer (BC); however, no clear survival benefit of BRRM over BC surveillance has been reported yet." (PMID 31302855, 2019). "For probands, the mean age at diagnosis of breast cancer in BRCA1 carriers was significantly earlier than non-carrier (41.8 vs 44.8 years, p=0.02)." (PMID 29861850, 2018). "Although LHRHa, AIs and SERMs are used in breast cancer and fertility treatments, there are no published data in the context of BRCA1-specific chemoprevention where the intention is to prevent ER-negative breast cancer." (PMID 30580266, 2018). "Our goal was to characterize BRCA1 and BRCA2 germline mutations in a group of very young Brazilian patients and to identify somatic mutations in luminal HER2 negative breast cancer." (PMID 29854292, 2018). "BRCA1 represses miR-155 expression in human breast cancer cell lines, and treatment with HDAC inhibitors rescues miR-155 level in wild-type, but not BRCA1-deficient cells." (PMID 30558184, 2018). "Multi-gene panel testing revealed no mutations in the mismatch repair, BRCA1/2, or PTEN genes but a deleterious frameshift mutation in RAD50, a moderate penetrance breast cancer gene." (PMID 30093976, 2018). "It is unclear that BRCA1 down-regulation is a prominent feature of triple-negative breast tumors, or it must be noticed as a more general molecular alteration in breast cancer regardless of tumor subtype." (PMID 28646826, 2018). "Our results support that HRR deficiency provides the basis of PARP inhibition sensitivity in vivo and is frequent among tumors without germline mutations in BRCA1/2 genes, in line with the frequency of HRD genomic signature among breast cancer patients." (PMID 30377213, 2018). "BRCA1 and ERBB2 splicing, as well as splicing of BCL-X and MCL-1 are examples of common driver oncogenes and tumour suppressor genes that can be aberrantly spliced in breast cancer." (PMID 29848666, 2018). "BRCA1 was downregulated in both cancer-free woman carriers and breast cancer patients but not in newborn carriers." (PMID 30049288, 2018). "When ductal lavage was performed on asymptomatic BRCA1/2 mutation carriers, the cells within the lavage fluid of 8/19 women showed promoter hypermethylation of at least one of four genes (BRCA1, BRCA2, ERα, and RARβ2) that are often hypermethylated in breast cancer." (PMID 29614786, 2018). "In contrast to BRCA-1 tumours, breast cancer arising from BRCA2 mutation do not differ from sporadic cancer with regard to distribution of breast cancer subtypes, the luminal forms expressing estrogen and progesterone receptors being the most frequent." (PMID 30544963, 2018). "For the same reasons, the presence of double mutations of BRCA1 and BRCA2 is extremely rare in the general population, although not exceptional in Ashkenazi breast-cancer patients." (PMID 29346284, 2018). "We showed that for BRCA1 and BRCA2 mutation carriers breast cancer risk was not increased after exposure to ovarian stimulation for IVF." (PMID 29937543, 2018). "In this work, in order to characterize the main role of BRCA1-induced metabolic reprogramming, we performed DIGE experiments coupled with LC_MS/MS analysis to profile the mitochondria proteome of breast cancer cells expressing or not BRCA1." (PMID 29584711, 2018). "Interestingly, a study enrolling 76 breast cancer patients reported that overexpression of miR-25*, miR-142-3p, miR-505*, miR-1248, miR-181a-2*, and miR-340* could discriminate between tumor samples from BRCA1/2 mutation carriers and non-carriers." (PMID 29765562, 2018).
breast cancer (continued). "BRCA1 conditional knockout mouse breast cancer tissue exhibited over expression of β‐hCG while BRCA1 expressing human breast cancer tissues did not express β‐hCG." (PMID 29460395, 2018). "A total of 568 breast cancer cases occurred in first-degree relatives, with an incidence of 21.3%, 20.4, and 8.4% for BRCA1, BRCA2 and non-carrier families, respectively." (PMID 29861850, 2018). "In breast cancer, HOXA9 and its downstream target BRCA1 are significantly downregulated, which was thought to be critical for the development of breast cancer in patients lacking estrogen receptor/progesterone receptor expression." (PMID 29662084, 2018). "These deletions are generally extensive and affect BRCA1 along with several other genes, including BECN1, suggesting that the deletion of BRCA1, not the deletion of BECN1, is the driver mutation in breast cancer." (PMID 30540126, 2018). "A BRCA1/2A preclinical mechanistic study reported that down-regulation of miR-25 by isoliquiritigenin resulted in increased autophagic cell death by overexpression of ULK1 and induced chemosensitization in MCF7/ADR breast cancer cells." (PMID 29765562, 2018). "Some Nigerian patients with breast cancer were previously screened for a few specific alleles of BRCA1 and BRCA2,5-8 but no African population has been evaluated for all known and candidate breast cancer genes." (PMID 30130155, 2018). "The difference regarding onset age of breast cancer between the BRCA1- and BRCA2-group was not statistically significant." (PMID 29176636, 2018). "We performed BRCA1/2 testing by next-generation sequencing in clinically sporadic breast cancer patients with medullary like breast cancer and without known BRCA1 and BRCA2 mutations at presentation." (PMID 29453630, 2018). "IHC and western blot analysis confirmed the expression of Brca1 and ERα in regenerated mammary tumors by p18−/− tumor cells and lack of Brca1 and ERα in regenerated tumors by p18−/−;Brca1MGKO cells with E2 supplement." (PMID 29996906, 2018). "In HepG2, top CPs were “hereditary breast cancer signaling”, “NRF2- mediated oxidative stress response”, “role of BRCA1 in DNA damage response”, “ATM signaling”, “cell cycle control of chromosomal replication”, “estrogen mediated S-phase entry” and “GADD45 signaling”." (PMID 30042885, 2018). "By contrast, double heterozygosity of mutations in the DNA repair genes BRCA1 and BRCA2 in patients with breast cancer was found to be no more deleterious than a single heterozygous mutation." (PMID 29706558, 2018). "In addition, anti-cancer therapy which combine PARP inhibition and genotoxic chemotherapeutic agents according to the expression of PARP1, γH2AX, BRCA1, and BRCA2 has been suggested for breast carcinomas and Ewing sarcomas." (PMID 29784019, 2018). "Triple negative breast cancers show lack of BRCA1 expression in addition to enhanced basal, epithelial-to-mesenchymal transition (EMT), and TIC phenotypes." (PMID 28052035, 2017). "Preclinical models show that PARP inhibition selectively targets breast cancer cells lacking functional BRCA1." (PMID 28359295, 2017). "When tumors were classified according to their basal nature using basal cell markers (CK5/6 and EGFR), basal-like breast cancer had significantly higher nuclear and cytoplasmic BRCA1 H-score (p<0.0001) and lowered N/C ratio than the non-basal tumors." (PMID 28863181, 2017). "In breast cancer cells, there are two negative transcriptional regulators of miR-155, BRCA1 and p63." (PMID 28562349, 2017). "The number of non-proband women diagnosed with breast cancer was too small to estimate the penetrance of BRCA2 mutations (two non-proband cases), and separate BRCA1 mutations (n = 7 for 3450del4 and n = 3 for A1708E)." (PMID 28680148, 2017). "We screened a cohort of 166 BRCA1/2 mutation-negative HBOC patients, of which 56 developed early-onset breast cancer before the age of 36 years, for GT198 variants." (PMID 28435519, 2017).
breast cancer (continued). "We performed a comprehensive analysis of BRCA1 and BRCA2 genes by Sanger sequencing and multiplex ligation‐dependent probe amplification (MLPA) to detect large rearrangements in patients from 18 families, which met the criteria for hereditary breast cancer." (PMID 28944232, 2017). "Taken together, these data show that in breast cancers in human or in animal models IRISOE tumors show lack of BRCA1 expression." (PMID 28052035, 2017). "Subsequent linkage studies have been performed in non-BRCA1/2 families, without identifying any novel putative breast cancer genes." (PMID 29262523, 2017). "In contrast, induced expression of RNF144A did not significantly affect the protein levels of BRCA1, another key DNA repair protein in breast cancer cells." (PMID 29212245, 2017). "This dataset contained 12 BRCA1- and 1 BRCA2-mutated hereditary breast tumors, 8 BRCAx (non-BRCA1/2 mutations, donated as non-BRCA) hereditary breast tumors, 14 sporadic breast cancer samples and 6 normal samples." (PMID 29146938, 2017). "Of note, transfection of BRCA1 shRNAs into FOXP3 Tet-off MCF7 cells reduced the induction of miR-155 by FOXP3, indicating the existence of a transcriptional mediator, BRCA1, between FOXP3 and miR-155 in human breast cancer cells." (PMID 28562349, 2017). "Since BRCA1 is destabilized in the absence of Rak, we evaluated a correlation between Rak and BRCA1 expression on breast cancer tissue microarrays by immunohistochemistry." (PMID 29156836, 2017). "In addition, UBE2T is overexpressed in breast cancer and silencing of UBE2T upregulates BRCA1 protein." (PMID 29156836, 2017). "Moreover, the median frequency of DMD alterations in sporadic breast cancer was higher than the median frequency for BRCA genes in the same tumors (3.95% vs 1.95% and 3.40% for DMD, BRCA1 and BRCA2, respectively)." (PMID 27391342, 2017). "The present study provides methylation levels for the promoters of APC, BRCA1, CDKN2A, ESR1, ESR2, HER2/neu and PTEN, CDKN2A exon 2 and LINE-1 in tumor, tumor-adjacent and tumor-distant tissues from 18 breast cancer patients and normal breast tissues from four healthy women." (PMID 28403857, 2017). "Following genetic counseling about the BRCA1 deletion, genetic testing was performed on her daughter and three sisters without breast cancer and her daughter was found to have the same deletion." (PMID 28205045, 2017). "BARD1 mutations are expected to account for additional cases of non-BRCA1/2 inherited breast cancer and have been reported in non-BRCA mutated breast cancer families." (PMID 29292755, 2017). "BRCA1-IRIS overexpression drives expression of basal biomarkers, epithelial to mesenchymal transition (EMT)-inducers and stemness-enforcers in breast cancer cells." (PMID 28499366, 2017). "PM yields a risk reducing effect of more than 90-100% in healthy BRCA1 and BRCA2 mutation carriers and PBSO decreases breast cancer risk in BRCA mutation carriers without prior breast cancer approximately by 50%." (PMID 28977823, 2017). "To focus our examination of transactivation of the ER promoter by BRCA1 in a cell type relevant to its role as a tumor suppressor gene in breast cancer, we performed all experiments with two human nontumorigenic mammary epithelial cell lines." (PMID 28270739, 2017). "In this study we aimed at comparing the effect of BRCA1-IRIS overexpression on the clinico-pathological characteristics in breast cancer patients with TNBC or non-TNBC in the largest comprehensive cancer center in Egypt." (PMID 28499366, 2017). "It has been recommended that young women with personal history of breast cancer should be considered for genetic counseling, and BRCA1/2 testing even when not meeting familial criteria." (PMID 29121898, 2017). "We have therefore endeavored to elucidate the molecular basis of the ER-negative phenotype in breast cancers lacking BRCA1." (PMID 28270739, 2017).
breast cancer (continued). "Although the patient had previous negative BRCA1/2 testing, her clinician ordered a larger breast cancer panel based on her age at diagnosis and striking family history." (PMID 28766213, 2017). "Inhibition of estrogen receptor function decreases breast cancer risk in healthy BRCA2 mutation carriers, but not in BRCA1 mutation carriers." (PMID 28977823, 2017). "In contrast to BRCA1 and p63, which are transcriptional repressors of miR-155, FOXP3, a member of the forkhead-box/winged-helix transcription factor family, is a transcriptional inducer of miR-155 in the breast cancer cell lines, BT549 and MDA-MB-231." (PMID 28562349, 2017). "No pathogenic variants in BRCA1, BRCA2 and other classical breast cancer-predisposition genes were present in these five families." (PMID 28076423, 2017). "The lack of pathogenic variants in BRCA1, BRCA2 and other predisposition genes indicates that these five families are all BRCAx breast cancer family." (PMID 28076423, 2017). "The index patient with a deletion of BRCA1 exon 19 had a personal history of early-onset, bilateral, triple-negative breast cancer, had 2 close blood relatives with breast cancer and also had 7 close blood relatives with cancers other than breast or ovary." (PMID 28351343, 2017). "Conditional inactivation of Bard1 in mice induces mammary carcinomas that are indistinguishable from carcinomas induced by conditional knock-out of Brca1, which establishes BARD1 itself as a tumor suppressor." (PMID 29292755, 2017). "Based on BRCA1 and RAD51 knockdown expression profiles and primary breast tumor expression data, we provide a computational method to infer the cell proliferation level for each breast cancer patient." (PMID 27788678, 2016). "About 10% of Brca1+/− or Brca1f/f;MMTV-cre mice develop mammary tumors by 18 months of age." (PMID 27811360, 2016). "It is possible that CtIP has weak tumor suppression activity (relative to BRCA1) such that its inactivation does not appreciably affect the kinetics of mammary tumor formation in our mouse model." (PMID 27058754, 2016). "Compared with women without mutations, those with somatic mutations in BRCA1 and BRCA2 genes are at increased risk for the development of breast cancer (life time breast cancer risk of 50–80%)." (PMID 27149669, 2016). "However, directed analyses showed that BRCA1 and HORMAD1 are clear candidates for driver genes directly regulated by aberrant methylation in some basal-like breast cancers." (PMID 26923702, 2016). "Interestingly, most of these key repair genes, including BRCA1, RAD51, RAD54L and BLM, were also identified in this study as E2F1 targets in breast cancer." (PMID 27666291, 2016). "BRCA1 and BRCA2 genes explain a large part of hereditary breast cancer." (PMID 27129401, 2016). "To determine if these changes were universal to cancer and not restricted to lymphoid cells, we analyzed the breast cancer cell lines T47D and HCC1937 (with BRCA1 mutation)." (PMID 26991404, 2016). "For the forty breast cancers studied, the mean age at diagnosis was 34.62 years for BRCA1/2 positive and 37.06 years for BRCA negative cancers." (PMID 26997744, 2016).
breast cancer (continued). "Moreover, genetic analyses showed that the BRCA1 founder mutations and polymorphism in P450 1A1 and CYP17 might increase risk among Greenlandic women A study in southern Quebec found an association between increased levels of PCBs, particularly PCB105, PCB118 and PCB156, and breast cancer." (PMID 27974137, 2016). "In our study, we prospectively selected 154 breast cancer patients and evaluated BRCA1 promoter methylation level in 154 paraffin-embedded breast cancer and 154 adjacent non-tumorous breast specimens." (PMID 27027444, 2016). "Although there are strong implications of PR involvement in BRCA1-related breast carcinogenesis, the effect of selective PR modulators (SPRMs) on breast cancer prevention has not yet been evaluated in humans." (PMID 27246982, 2016). "However the expression of an ER-inducible gene involved in the migration of human breast cancer cells, the trefoil factor 1 (TTF1 or pS2), was decreased in BRCA1+/mut tissues." (PMID 27246982, 2016). "BRCA1 and BRCA2 mutations in breast cancer patients have not been characterized in the Uzbek population." (PMID 29138730, 2016). "To date, BRCA1 and BRCA2 mutations in breast cancer patients have not been characterized in the Uzbek population." (PMID 29138730, 2016). "Since BRCA1 is a relevant driver in breast cancer we analyzed gains and losses in these tumors to correlate the absence of BRCA1 protein to specific genomic alterations." (PMID 26979459, 2016). "An example for cancer-related genes under negative selection is breast cancer 1, early onset gene (BRCA1)." (PMID 27313952, 2016). "Although this is a region frequently affected in breast cancer irrespective of the molecular subtype and ethnicity, it has been observed preferentially amplified in TNBC, including the ones that present BRCA1 mutations, which are frequently in AA women." (PMID 27813494, 2016). "In breast cancer, we have demonstrated that FOXC1 plays a role in proliferation in BRCA1-mutant BLBC cells, and prior studies have demonstrated a critical role for FOXC1 in the functional properties of BLBC, driving metastasis, epithelial-mesenchymal transition phenotype, and tumorigenesis." (PMID 27708239, 2016). "Equol modulates expression of the BRCA1 and BRCA2 breast cancer genes through an epigenetic mechanism resulting in decreased methylation, which results in an increased level of oncosuppressors in breast cancer cell lines." (PMID 28149839, 2016). "Germline mutations in the BRCA1 and BRCA2 genes in patients with early-onset breast cancer have not been clearly identified within the Algerian population." (PMID 26997744, 2016). "BRCA1 mutant, triple negative HCC1937 and MX1 breast cancer cells were used for the study." (PMID 27220670, 2016). "Several tumor-suppressive genes such as BRCA1, TIMP1 and ERα are hypermethylated in breast cancer." (PMID 26418898, 2016). "Further support was provided by our in silico analysis showing that BRCA1 candidate proteins, when mapped to mRNA transcripts, could cluster BRCA1- and BRCA2-related breast cancer cases." (PMID 27566577, 2016). "Nevertheless, mammary-specific inactivation of either the Brca1, Bard1, or Brca2 gene readily induces mammary tumors despite the fact that mice lacking expression of these genes also die during early embryogenesis." (PMID 27058754, 2016). "In this first Moroccan study comparing clinical and pathological characteristics of women carrying or not BRCA1/2 mutation, patients with BRCA mutation tend to develop early breast cancer with high-grade and triple negative tumors." (PMID 27129401, 2016).